MDM2 (MDM2 proto-oncogene)
Diseases named in the same sentence as MDM2 in open-access papers (continued):
Sharing a sentence is not in itself a finding about the gene and the disease.
lipoma (continued). "Eventually 328 patients were excluded due to unknown MDM2 status or disease other than lipoma or ALT." (PMID 39351025, 2024). "Therefore, the aim of this study was to develop and validate radiogenomic machine-learning models to predict the MDM2 gene amplification status in order to differentiate between ALTs and lipomas on preoperative MR images." (PMID 37046811, 2023). "It is possible that some of these patients without MDM2 testing had lipomas or lipoma variants and not bona fide ALT, though prior studies have demonstrated that ALTs can be diagnosed by histologic criteria alone." (PMID 36046749, 2022). "In an ongoing work, we could demonstrate promising results differentiating benign lipomas from atypical lipomatous tumors based on the murine double minutes (MDM2) gene amplification status." (PMID 33923697, 2021). "A previous study found that MDM2 is highly sensitive for atypical lipomatous tumor, and without taking this marker into account, there has been a tendency to misclassify atypical lipomatous tumors as lipomas in the past." (PMID 32997268, 2020). "Therefore, the purpose of this study was to assess the reliability of MR imaging criteria of ALTs and lipomas using the histopathology and the MDM2 amplification status by FISH as a standard of reference." (PMID 30943944, 2019). "A previous study that had assessed the reliability of MR imaging characteristics of lipomas and ALTs, diagnosed with histopathological features as well as the MDM2 amplification status showed an overall excellent sensitivity, yet a very poor specificity using the criteria assessed." (PMID 30943944, 2019). "The gene copy number (mean levels) of lipoma was 0.8 and 0.9 for MDM2 and CDK4, respectively." (PMID 25176350, 2014). "Therefore, the aim of this study was to develop and validate radiogenomic machine-learning models based on multiparametric MR examinations to predict the MDM2 gene amplification status in order to differentiate between ALTs and lipomas on preoperative MR images." (PMID 37046811, 2023). "Immunohistochemical analysis revealed that the tumor was CK(−), MDM2(−), CDK-4(−), S-100(+), CD34(+), HNB45(−), Mela-A(−), 1% ki67(1%+), focal Desmin(+), and focal SMA(−), indicating a differentiated mature lipoma with mild fibrosis." (PMID 37492162, 2023). "The technique of fluorescence in situ hybridization (FISH) has proven to be extremely valuable in assessing the MDM2 status in cases where distinguishing between ALT/WDLS and benign lipomatous neoplasms is challenging based solely on morphological features." (PMID 38132190, 2023). "HMGA2 is often coamplified with MDM2 in WDLPS and DDLPS, but more commonly altered in benign lipomas." (PMID 37298520, 2023). "More importantly, MDM2 and CDK4 nuclear positivity, especially MDM2 gene amplification, can be invaluable in distinguishing WDL from lipoma and inflammatory lesions." (PMID 36059611, 2022). "Although the diagnostic accuracy of our combined scoring system for ALT/WDLS was slightly lower than that of FISH for MDM2, our scoring system will help to preoperative differential diagnosis between ALT/WDLS and lipoma." (PMID 34997060, 2022). "Nine cases of lipoma were received with a request to exclude WDL, of which FISH for MDM2 amplification was performed in eight and found to be negative." (PMID 33061792, 2020). "Of 113 mature lipomatous tumors, 66 were diagnosed as lipomas and 47 as ALT using the MDM2 amplification status by FISH as standard of reference." (PMID 30943944, 2019). "The goal was to reassess the ability of expert observers to distinguish lipoma from ALT/WDL on MRI, given the increased accuracy of pathologic diagnosis of these tumors using MDM2 as the gold standard." (PMID 29755284, 2018).
lipoma (continued). "While MDM2 FISH has affected the confidence with which pathologists can diagnose ALT/WDLs, it remains difficult for expert observers to distinguish them from benign lipomas on imaging." (PMID 29755284, 2018). "Following MDM2 FISH, the pathologic diagnosis was subsequently confirmed to be a benign lipoma, increasing the accuracy of our readers and the formula." (PMID 29755284, 2018). "Relative MDM2 and CDK4 expression levels in lipoma and ALT/WDL cases with a ring and/or giant chromosome were higher than those with 12q13-15 rearrangements and other abnormal karyotypes (P < 0.05, Steel-Dwass test)." (PMID 24965044, 2014). "We evaluated the clinical utility of measuring MDM2 and CDK4 expression levels to establish a diagnosis of adipocytic tumors, with the aim of making a distinction between lipoma and ALT/WDL." (PMID 24965044, 2014). "In this study, we used whole tissue sections from surgically resected specimens to retrospectively analyze cytogenetic findings by quantifying MDM2 and CDK4 expression levels in lipomas and ALT/WDL with real-time polymerase chain reaction (PCR) from total RNA." (PMID 24965044, 2014). "In whole tissue sections, the medians for MDM2 and CDK4 expression in ALT/WDL were higher than those in the lipomas (P < 0.05)." (PMID 24965044, 2014). "In this study, MDM2 and CDK4 expression levels, as determined by real-time PCR, were higher in ALT/WDL than in lipoma samples in whole tissue sections (P < 0.05)." (PMID 24965044, 2014). "The gene expression levels of MDM2 and CDK4 were studied in 149/168 whole tissue sections (108 lipoma samples and 41 samples from the 38 cases of ALT/WDL)." (PMID 24965044, 2014). "Both MDM2 and CDK4 relative expression levels in ALT/WDL were higher than those in lipoma (P < 0.05, Mann–Whitney U test)." (PMID 24965044, 2014). "The relative gene expression levels of MDM2 and CDK4 were studied in 38/168 samples (28 lipoma samples and 10 ALT/WDL samples) from core-needle biopsy sections." (PMID 24965044, 2014). "All lipomas displayed a null MDM2/CDK4 phenotype, whereas all LL-WDL showed MDM2/CDK4 or CDK4 phenotypes." (PMID 10755400, 2000). "As per the definition, MDM2 amplification was significantly more common in ALTs (p < 0.01), although one ALT was negative, requiring additional cyclin-dependent kinase 4 (CDK4) testing to differentiate it from a lipoma in this specific case." (PMID 40564858, 2025). "Among them, 69 patients had lipomas with negative MDM2 amplification, 37 had proven ALTs, and 82 had a pathology report labelling them as lipomas but without molecular pathology testing." (PMID 40564858, 2025). "Two radiologists, blinded to the final diagnosis, independently assessed various features on conventional magnetic resonance imaging (MRI), in 79 patients with pathologically confirmed fatty tumors as either lipoma (MDM2 negative) or ALT (MDM2 positive)." (PMID 39997549, 2025). "Accordingly, a negative MDM2 result can distinguish a lipoma from a WDLPS, preventing an unnecessary wider surgical excision in some cases, as was the case in one of our patients." (PMID 39001377, 2024). "Molecular confirmation by FISH for lack of MDM2 amplification is highly recommended to render a reliable diagnosis of retroperitoneal lipoma." (PMID 37131332, 2024). "Previous studies have shown that the MDM2 amplification status is the most accurate marker to differentiate ALTs and lipomas, and there is a tendency towards sampling errors if the MDM2 status is not determined." (PMID 37046811, 2023). "The mean concordance rate of identifying samples as lipoma or ALT/WDL based on cytological and histopathological findings was 76.7% (65% minimum, 90% maximum), whereas that based on cytological findings and MDM2 amplification by FISH was 78.3% (70% minimum, 85% maximum)." (PMID 34984861, 2022).
lipoma (continued). "Since the sensitivity of large atypical cells, which are distinctive for WDLPS, is not high, the MDM2 testing facilitates the differentiation of WDLPS from lipoma preoperatively." (PMID 36555969, 2022). "If the sum of the scores for the multinucleated cells, pleomorphism, and large atypical cells was 3 for lipoma and 4–12 for ALT/WDL, and the MDM2 amplification indicated ALT/WDL, positive sensitivity was 90.3%, negative sensitivity was 64.6%, and the total concordance rate was 80.0%." (PMID 34984861, 2022). "Nowadays, the standard way to differentiate WDLPS from lipoma applies fluorescence in situ hybridization (FISH) in biopsy samples that amplification of the MDM2 gene is absent in lipoma, but present in WDLPS." (PMID 35392952, 2022). "In our study, of the 23 cases diagnosed histologically as WDLS, 15 cases were negative for MDM2 amplification and were reclassified as either undifferentiated sarcomas or lipomas." (PMID 36164527, 2022). "In this study, we hypothesized that multimodality (CT and MRI) deep learning methods could be implemented to evaluate amplification of MDM2 gene in order to classify WDLPS and lipoma." (PMID 35392952, 2022). "Although the amplification of the 12q13–15 region, carrying the MDM2 andCDK4 genes, is used to distinguish WD/DDLPS and ALT from benign lipomas and from other types of liposarcomas, specific aberrations that can be used to distinguish between WDLPS and DDLPS subtypes have not been identified so far." (PMID 32158531, 2020). "True retroperitoneal lipomas are rare but increasingly recognized and show clinicopathologic and genetic features (including lack of MDM2 amplification) more akin to lipomas than WDL such that their identification by FISH is prognostically useful." (PMID 25810689, 2015). "In MLSLC, the tumor cells were uniformly negative for CDK4 and MDM2 in both lipoma-like and myxoid areas." (PMID 25650275, 2015). "Conversely, ring/giant marker chromosomes as well as immunohistochemical expressions of CDK4 and MDM2 characteristic of ALT/WDLS were never found in any case of MLS with a lipoma-like component." (PMID 25650275, 2015). "Amplification of the 12q13-15 region has not been observed in lipoma, and the MDM2 and CDK4 proteins are known to be overexpressed in ALT/WDL but not in lipoma." (PMID 24965044, 2014). "Consequently, a significant proportion of presumed lipomas without MDM2 amplification analysis were likely ALTs according to our model." (PMID 40564858, 2025). "Thus, FISH testing of MDM2 and CDK4 gene amplifications provides greater accuracy in the diagnosis of ALT/WDLS and is considered the gold standard for differentiating it from a lipoma." (PMID 38132190, 2023). "Their best-performing model achieved an accuracy of 95% at 100% sensitivity and 90% specificity using the histology as the reference standard, though no specific information regarding the MDM2 gene amplification status was included, which may have led to a false classification of ALTs as lipomas." (PMID 37046811, 2023). "However, the majority of intracardiac lipoma is negative for MDM2 amplification." (PMID 37492162, 2023). "Therefore, immunostaining of MDM2 may not be a useful tool for the differential diagnosis of lipoma and ALT/WDL in cytology." (PMID 34984861, 2022). "However, few multinucleated cells were observed in lipoma cases without MDM2 amplification." (PMID 34984861, 2022). "Moreover, the expression of MDM2 and CDK4 in whole tissue sections was compared with that in core-needle biopsy sections of the same tumor in order to determine whether real-time PCR could be used to distinguish ALT/WDL from lipoma at the preoperative stage." (PMID 24965044, 2014). "Moreover, we compared the results of MDM2 and CDK4 expression in whole tissue sections with those in core-needle biopsy sections in order to investigate whether real-time PCR for MDM2 and CDK4 could be used to distinguish between ALT/WDL and lipoma prior to surgery." (PMID 24965044, 2014).
lipoma (continued). "If this is true, the rarely observed coamplification of centromere-related oncogenes, such as MDM2 and D12Z3 amplicons in lipomas, would be the exception rather than the rule for this type of amplicon formation." (PMID 40097918, 2025). "Spindel cell lipomas consist of bland spindle cells and are positive for CD34 and negative for MDM2 and CDK4." (PMID 40777097, 2024). "Nor is there, as shown here, any clear-cut border between lipoma and WDLS with regard to HMGA2 status or MDM2 CN level or expression levels of these two genes, providing molecular support for the existence of an intermediary tumor type." (PMID 38769442, 2024). "Yet, the major limitation of this study was, beside the small cohort size, that the standard of reference was inadequate due to the lack of MDM2 amplification status assessment or the assessment of other cytogenetic markers, and thus, several actual ALTs may have been falsely classified as lipomas." (PMID 30943944, 2019). "A previous study has shown that MDM2 is highly sensitive for ALT and that without taking this marker into account there has been a tendency to falsely classify ALTs as lipomas in the past." (PMID 30943944, 2019). "On the other hand, WDLS and DDLS were variably positive for CDK4 and MDM2, presenting a sharp contrast to MLS with or without lipoma-like components." (PMID 25650275, 2015). "The staining for MDM2 (MDM2 proto-oncogene) and CDK4 (cyclin-dependent kinase 4) was negative, therefore the lesion was diagnosed as a lipoma." (PMID 25890295, 2015). "MDM2 FISH demonstrated no gene amplification, confirming benign lipoma." (PMID 42253355, 2026). "Immunohistochemistry may be of help since markers such as MDM2 and CDK4, commonly evaluated in soft tissue tumors, are typically negative in lipoma cases." (PMID 40729232, 2025). "In these cases, cell block preparation with MDM2 and CDK4 immunohistochemistry can be used to assess for positive nuclear staining, along with FISH studies for amplification of MDM2 for WDLPS (negative in thymolipoma or lipoma)." (PMID 37510144, 2023). "We also show that this assay was highly specific for detecting MDM2 amplification in the circulation of patients with DDLPS, as this aberration was not detectable in cell-free DNA of patients with lipoma, pleomorphic liposarcoma, undifferentiated sarcoma or LMS." (PMID 34986184, 2022). "However, a detailed comparison of the cytological findings of lipoma and ALT/WDL with MDM2 amplification has not yet been reported." (PMID 34984861, 2022). "Subsequent MDM2 FISH was negative for gene amplification, and given the histologic concern for atypia, the FISH was again repeated and found to again be negative, confirming the diagnosis of lipoma and changing the pathologic diagnosis." (PMID 29755284, 2018).
lymphoma (57 papers, 2009 to 2025). A malignant (clonal) proliferation of B- lymphocytes or T- lymphocytes which involves the lymph nodes, bone marrow and/or extranodal sites. "In our results, we detected different patterns in the different lymphoma types examined regarding the relative abundance of the MDM2 isoforms, indicating different mechanisms and effects of MDM2 in these lymphoma types." (PMID 37568720, 2023). "A phase 1 trial presented at the 2018 annual American Society of Clinical Oncology meeting used an oral MDM2 inhibitor, DS‐3032b to treat LPS, lymphoma, and solid tumors." (PMID 36464833, 2023). "Siremadlin (HDM2) was also found safe and capable of inhibiting MDM2 in solid malignancies and lymphomas." (PMID 37314603, 2023). "We demonstrate that there is decreased NUMB and increased MDM2 expression in NOTCH1 overexpressing lymphomas." (PMID 37160922, 2023). "We found that overexpression of HDAC1 and MDM2 correlated with the presence of lymphomatous effusions, and HDAC1 overexpression also was associated with a poorer prognosis (p = 0.005)." (PMID 34635181, 2021). "MDM2 inhibitors have been already proposed for the development of lymphoma driven by Epstein-Barr virus EBV nuclear antigen-1 (EBNA1)." (PMID 32268515, 2020). "MDM2 inhibitors e.g., Nutlin-3a, SAR405838, and JNJ-26854165, or c-Abl kinase inhibitor e.g., Nilotinib, can suppress the growth of lymphomas in EμEBNA-1 transgenic mice via the EBNA-1/MDM2/E2F1 pathway." (PMID 30873380, 2019). "We have now performed pathology on this cohort and found that 30% (3 out of 10) of the irradiated Mdm2P2/P2 and Mdm2+/+ mice also developed lymphomas." (PMID 24658419, 2014).